FOXO1 (forkhead box O1)
Diseases named in the same sentence as FOXO1 in open-access papers (continued):
Sharing a sentence is not in itself a finding about the gene and the disease.
Ewing sarcoma (42 papers, 2005 to 2025). A small round cell tumor that lacks morphologic, immunohistochemical, and electron microscopic evidence of neuroectodermal differentiation. "In accordance with this, primary Ewing sarcoma exhibits lower levels of FOXO1 expression compared to other tissues." (PMID 37894854, 2023). "We confirmed DNA-binding specificity of the purified protein by comparing its binding with oligonucleotides specific for PAX3::FOXO1 or EWS::FLI1 (a tumor-specific fusion oncoprotein found in Ewing sarcoma) using SPR." (PMID 37732905, 2023). "FOXO1 has been described as a key regulator of Ewing’s sarcoma, but the role of FOXO3 is less clear." (PMID 37242535, 2023). "To better understand the clinical applicability of cfDNA assays, we developed a hybridization capture-based panel targeting the most common translocation partners in two pediatric cancers, specifically EWSR1 for Ewing sarcoma and FOXO1 in ARMS5." (PMID 36805676, 2023). "When FOXO1 was induced in two Ewing sarcoma cell lines, A673 and SKNMC, it led to reduced cell proliferation and diminished capability to form colonies in soft agar." (PMID 37894854, 2023). "The treatment of Ewing sarcoma cells with MSA resulted in the induction of FOXO1 expression in a concentration-dependent manner, and this correlated with cell death through apoptosis." (PMID 37894854, 2023). "These discoveries highlight that EWS/FLI1 inhibits FOXO1 activity through multiple mechanisms within Ewing sarcoma cells." (PMID 37894854, 2023). "In accordance with this, FOXO1 is expressed at lower levels in primary Ewing sarcoma as compared to other tissues." (PMID 26258070, 2015). "Treatment of Ewing sarcoma cells with MSA induced FOXO1 expression in a concentration-dependent manner, which correlated with apoptotic-mediated cell death." (PMID 26258070, 2015). "Since FOXO1 acts as a tumor suppressor in Ewing sarcoma, a valuable therapeutic approach can consist in the reactivation of FOXO1 activity." (PMID 26258070, 2015). "Given FOXO1’s role as a tumor suppressor in Ewing sarcoma, a promising therapeutic strategy could involve the reactivation of FOXO1." (PMID 37894854, 2023). "As the reactivation of FOXO1 has demonstrated effectiveness in Ewing sarcoma cells in both laboratory settings (in vitro) and living organisms (in vivo), further research is imperative to unravel the intricate mechanisms governing FOXO1 expression and its transcriptional activity." (PMID 37894854, 2023). "Since reactivation of FOXO1 in Ewing sarcoma cells has shown to be effective both in vitro and in vivo, more studies are necessary to understand the mechanism involved in the regulation of FOXO1 expression and its transcriptional activity in order to identify new therapeutic targets." (PMID 26258070, 2015). "EWS/FLI1 binds to the FOXO1 promoter and represses its expression in Ewing sarcoma cells." (PMID 26258070, 2015). "A large diversity offusion oncogenes was observed, primarily in one tumor, the three most commonbeing: EWSR1::Fli1 (n = 13) observed in Ewing sarcomas, PAX3::FOXO1 (n = 12) inrhabdomyosarcomas, and ETV6::RUNX1 (n = 8) in childhood leukemias." (PMID 40093400, 2025). "Taken together, the relationship between LSD1 and PAX3/FOXO1 shows many parallels to LSD1 and EWS/FLI in Ewing sarcoma, supporting LSD1 as a promising therapeutic target in this disease." (PMID 36686841, 2022). "Like EWS/FLI of Ewing sarcoma, the PAX3/FOXO1 alters the function of other chromatin regulatory factors." (PMID 36686841, 2022). "Thus, methylseleninic acid, a drug reported to induce elevated expression of FoxO1 in ES cells, apoptosis of ES cells, and significant reduction of tumor growth in an orthotopic mouse xenotransplantation model, may be a potential target drug for Ewing sarcoma." (PMID 35153742, 2021).
Ewing sarcoma (continued). "CDKN1C and a related member of the FOXO family, FOXO1, have previously been shown to inhibit Ewing Sarcoma growth, while FOXM1, GLI1 and PDGFRB have been shown to be growth-promoting in Ewing Sarcoma." (PMID 30237855, 2018). "In Ewing sarcoma cells, EWS/FLI1 binds to the promoter of FOXO1 and suppresses its expression." (PMID 37894854, 2023). "Next, expression levels of eight EWS-FLI1 associated target genes (GLI1, NEX2.2, CyclinD, c-MYC, NR01B, IGF1R, EZH2, and CD99) which were known to be upregulated, and three genes (FOXO1, IGFBP3, and LOX) known to be down regulated in Ewing’s sarcoma was assessed." (PMID 28775288, 2017). "Induction of FOXO1 in two Ewing sarcoma cells (A673 and SKNMC) resulted in impaired cell proliferation and reduced soft agar colony formation capability, confirming that FOXO1 is a tumor suppressor in Ewing sarcoma and that its inhibition is important for Ewing sarcoma growth." (PMID 26258070, 2015). "Moreover, transcriptional regulation of FoxO1 by PARP1 is not just limited to Ewing sarcoma cells; similar changes were observed in CAPAN1 cells." (PMID 31992690, 2020).
osteosarcoma (41 papers, 2009 to 2026). A usually aggressive malignant bone-forming mesenchymal neoplasm, predominantly affecting adolescents and young adults. "In osteosarcoma cells, FOXO1 activation led to decreased CCND1 (encoding cyclin D1) expression." (PMID 37584250, 2023). "FOXO1 loss might contribute to the disturbed terminal differentiation observed in osteosarcoma." (PMID 30881341, 2019). "One study showed that liver X receptor α suppressed the proliferation of osteosarcoma cells via the promotion of FoxO1 expression." (PMID 39153212, 2024). "In our study, we found that inhibition of FoxO1 enhanced the proliferation, migration and invasion of osteosarcoma cells." (PMID 39153212, 2024). "In this study, we aimed to investigate the impact of circMRPS35 overexpression and its interaction with FOXO1 via evaluating apoptosis, cell cycle, and bioinformatic analyses on the malignant development of osteosarcoma in MG63 and MNNG/HOS cells." (PMID 39103205, 2024). "This action also activates FOXO1 expression and significantly inhibits the Wnt/β- catenin signaling pathway, which offers a potential therapeutic target for the treatment of osteosarcoma in humans." (PMID 38343056, 2024). "Trichostatin A (TSA), a histone deacetylase inhibitor (HDACi), induces autophagy in osteosarcoma cells by suppressing the AKT-mTOR signaling pathway and activating FoxO1, thereby enhancing the survival of osteosarcoma cells." (PMID 38486976, 2024). "Taken together, these findings indicated that the downregulation of FBXO22 repressed osteosarcoma cell proliferation by targeting the FoxO1 pathway." (PMID 39153212, 2024). "In osteosarcoma, FOXO1 acts as an inhibitory molecule in the WNT signalling pathway, promoting the upregulation of CCL4 expression." (PMID 38899748, 2024). "We observed that depletion of FBXO22 increased the expression of FoxO1 at the protein level in osteosarcoma cells." (PMID 39153212, 2024). "In the present study, we reported that FBXO22 plays a tumour‐promoting role in osteosarcoma cells via regulating the abundance of the FoxO1 protein." (PMID 39153212, 2024). "We observed that shFBXO22 transfection increased the expression of FoxO1 protein, which partly abolished the shFoxO1‐induced inhibition of FoxO1 in osteosarcoma cells." (PMID 39153212, 2024). "Our findings provide evidence for a novel mechanism by which FBXO22 promotes the degradation of the FoxO1 tumour suppressor in osteosarcoma in part." (PMID 39153212, 2024). "FoxO1 blocks osteosarcoma tumorigenesis through suppression of the Wnt/β‐catenin signalling pathway." (PMID 39153212, 2024). "Investigating the biological role and probable mechanism of the connection between FUT4 and FOXO1 in the development of osteosarcoma was the aim of this investigation." (PMID 38343056, 2024). "Overexpression of miR-506 upregulated the expression of p57 and FOXO1, which was abrogated by miR-506 mimic transfection in osteosarcoma cells." (PMID 33621206, 2021). "Apigenin and Luteolin treatments in osteosarcoma models showed Forkhead box protein O1 (FOXO1) translocation and reduced Glucose-6-Phosphatase (G6Pc) mRNA levels, as well as Phosphoenolpyruvate Carboxykinase (PEPCK), CAT, and SOD." (PMID 33918290, 2021). "Accordingly, miR-506 mimics reduced Skp2 expression and subsequently promoted the expression of downstream targets, FOXO1 and p57, in osteosarcoma cells." (PMID 33621206, 2021). "FOXO1 has been reported to negatively regulate MALAT1 by binding to its promoter in osteosarcoma cells." (PMID 32708561, 2020). "FOXO1 was also reported to negatively regulate MALAT1 by binding to its promoter in osteosarcoma cells." (PMID 32708561, 2020). "FOXO1 has been reported as a transcriptional factor of MALAT1 that negatively regulates MALAT1 in osteosarcoma cells." (PMID 32708561, 2020). "The same authors found five gains, six losses, and 15 cases of LOH of the FOXO1 locus in 34 cases of osteosarcoma by analysis of whole-genome sequencing." (PMID 30881341, 2019).
osteosarcoma (continued). "In osteosarcoma cell lines, the activation of FOXO1 promotes the pathway leading to cell cycle arrest and apoptosis that has been associated with repressed Wnt/β-catenin signaling." (PMID 30881341, 2019). "FOXO1 activation induces cell cycle arrest and its inhibition by impairing osteogenic differentiation of osteosarcoma cell lines considering that FOXO1 is a positive promoter of osteoblastogenesis in vitro." (PMID 30881341, 2019). "The inhibition of FOXO1 induced cell proliferation and decreased the osteogenic differentiation of osteosarcoma cells." (PMID 30881341, 2019). "A previous study reported that FOXO1-related lncRNA MALAT1 can inhibit osteosarcoma cell proliferation, indicating the presence of a class of lncRNAs regulated by FOXO1, which play important roles in PDAC progression." (PMID 31027497, 2019). "In osteosarcoma, FOXO1 can suppress osteosarcoma oncogenesis through suppression of Wnt/β-catenin pathway." (PMID 30360388, 2018). "Recently, FOXO1 was shown to inhibit osteosarcoma oncogenesis via wnt/β-catenin pathway suppression." (PMID 27835585, 2016). "We found that FHL2 silencing increased Foxo1 expression in osteosarcoma cells, suggesting a possible implication of Foxo1 in the anti-apoptotic effect of FHL2 silencing in osteosarcoma cells." (PMID 23383046, 2013). "Additionally, the active ingredients of HCSI inhibit tumor progression by enhancing FOXO1-mediated transcription of FCGBP in osteosarcoma." (PMID 40764575, 2025). "Therefore, we concluded that circMRPS35 suppressed the malignant progression of osteosarcoma via targeting the miR-105-5p/FOXO1 axis." (PMID 39103205, 2024). "Similarly, miR‐374a downregulates the expression of FoxO1 and promotes cell proliferation promotion in human osteosarcoma." (PMID 39153212, 2024). "Nevertheless, the mechanism behind how FUT4 and FOXO1 interact in osteosarcoma is unknown and requires more research." (PMID 38343056, 2024). "Furthermore, MG132 treatment blocked FoxO1 accumulation in osteosarcoma cells after cotransfection with Myc‐FBXO22 and Flag‐FoxO1." (PMID 39153212, 2024). "Determining the correlation between FBXO22 and FoxO1 in osteosarcoma tissues is critical." (PMID 39153212, 2024). "We hypothesize that there could be some interaction between FUT4 and FOXO1, which is crucial for osteosarcoma growth and metastasis." (PMID 38343056, 2024). "FBXO22 exhibited oncogenic functions in osteosarcoma cells via a reduction in the FoxO1 protein." (PMID 39153212, 2024). "In U-2 OS (human osteosarcoma) cells, apigenin could trigger rapid intracellular translocation of FOXO1 which was reversed by insulin." (PMID 38629096, 2024). "Additionally, miR‐196a enhances cell growth and reduces apoptosis by targeting the PTEN/Akt/FoxO1 pathway in osteosarcoma." (PMID 39153212, 2024). "However, the relationships among FBXO22, PD‐1, PD‐L1 and FoxO1 in osteosarcoma should be clarified for future immunotherapy application." (PMID 39153212, 2024). "To test whether depletion of FBXO22 affected cell motility by regulating FoxO1 in osteosarcoma cells, we performed Transwell migration and invasion assays in U2OS and SaOS‐2 cells after shFBXO22 transfection in combination with shFoxO1 treatment." (PMID 39153212, 2024). "Another study revealed that miR‐135b could accelerate cell proliferation and invasion via the inhibition of FoxO1 in osteosarcoma cells." (PMID 39153212, 2024). "Mechanistically, FBXO22 promoted the ubiquitination and degradation of FoxO1 in osteosarcoma cells." (PMID 39153212, 2024). "Consistently, FBXO22 overexpression reduced FoxO1 protein levels in osteosarcoma cells." (PMID 39153212, 2024). "Overexpression of FOXO1 or treatment with a miR-105-5p inhibitor could counteract the effects of circMRPS35 on viability and apoptosis in osteosarcoma cells." (PMID 39103205, 2024). "FOXO1 tumor suppressor activity inhibited the WNT pathway in osteosarcoma cell lines U2OS and MG63." (PMID 37584250, 2023).
osteosarcoma (continued). "The rebuilding of FOXO1 activity could be a potential therapeutic strategy for therapy of osteosarcoma." (PMID 30881341, 2019). "Stably transfected human osteosarcoma cells (U-2 OS) with constitutive expression of FOXO1 protein labeled with GFP (green fluorescent protein) were used to evaluate the effect of BITC on FOXO1." (PMID 27622707, 2016). "Apigenin and luteolin were identified in our U-2 OS (human osteosarcoma) cell screening assay for micronutrients triggering rapid intracellular translocation of the forkhead box transcription factor O1 (FOXO1), an important mediator of insulin signal transduction." (PMID 25136826, 2014). "However, whether FBXO22 affects the proliferation and motility of osteosarcoma cells by targeting FoxO1 and other proteins, such as p57, PTEN and MMP‐9, is elusive." (PMID 39153212, 2024). "In the present study, we report that AS1842856-mediated inhibition of FOXO1 reverses anticancer drug-induced cytotoxicity, while FADD knockdown increases anticancer drug-induced cytotoxicity in osteosarcoma (OS)." (PMID 41596582, 2026). "It has been reported that inhibition of Fucosyltransferase4 (FUT4) to activate Forkhead box O1 (FOXO1) can lead to apoptosis of cancer cells, however, the mechanism in osteosarcoma is still unclear." (PMID 38343056, 2024). "In MG63 osteosarcoma cells, HIF-1α was found to inhibit reactive oxygen species accumulation by directly regulating FoxO1, which interfered with CAT catalase activity, thus resulting in anti-oxidation effects." (PMID 37681913, 2023). "In osteosarcoma, MALAT1 can promote cancer metastasis, mediated by activation of the PI3K/Akt signaling pathway, and the FOXO1-MALAT1-miR-26a-5p feedback loop." (PMID 32708561, 2020). "miR-374 has been found to directly target forkhead box O1 (FOXO1), a member of the forkhead box (FOX) family and then stimulate cell proliferation and invasion in osteosarcoma." (PMID 32199127, 2020). "C3-Luc2.3-FoxO1 cells are a derivative of U2OS osteosarcoma cells with a doxycycline-inducible FoxM1-GFP fusion protein, a tamoxifen-inducible constitutively active FoxO1(AAA)-ER fusion protein and a FoxM1/FoxO1-dependent firefly luciferase." (PMID 19440351, 2009). "To determine whether FoxO1 is the substrate of FBXO22, we performed a Western blotting analysis in osteosarcoma cells after FBXO22 depletion or overexpression." (PMID 39153212, 2024). "The Wnt/β-catenin signaling pathway has a significant effect on osteosarcoma cell death, and inhibition of FUT4 expression may target FOXO1 activation to decrease osteosarcoma cells' ability to proliferate, invade, and migrate." (PMID 38343056, 2024). "Considering the versatile roles played by FOXOs in bone development and tumorigenesis, it is plausible that FOXO1, the main FOXO in bone with a non-redundant role, might have influence on osteosarcoma (OS) oncogenesis." (PMID 26344693, 2015).
bladder cancer (40 papers, 2015 to 2025). "As seen in AR signals, ERβ has been linked to a tumor suppressor FOXO1, as a downstream target, in bladder cancer cells." (PMID 40486871, 2025). "Further analysis of these bladder cancer samples revealed that lower FOXO1 expression was associated with higher clinical staging, greater lymph node metastasis, and poorer prognosis." (PMID 37174744, 2023). "The abnormal expression of FOXO1 was observed in metastatic bladder cancer cells and it was associated with poorer outcomes and recurrence in bladder cancer." (PMID 36430344, 2022). "In bladder cancer, down-regulation of FOXO1 was closely connected with worse results like high risk of recurrence, especially in high-grade tumors." (PMID 29221208, 2017). "Instead, our preliminary study showed that GR expression in bladder cancer tissue specimens detected by immunohistochemistry was positively and negatively associated with the expression of FoxO1 and its inactive form phospho-FoxO1, respectively." (PMID 30518063, 2018). "Moreover, FOXO1 was downregulated in bladder cancer, which was associated with poor outcomes." (PMID 32047567, 2020). "Meanwhile, in bladder cancer specimens, the expression of FOXO1 vs. ERα or ERβ was positively or negatively, respectively, correlated." (PMID 40486871, 2025). "The activity of ERβ and FOXO1 was inversely correlated, and ERβ-mediated FOXO1 inactivation resulted in the promotion of bladder cancer cell proliferation and migration." (PMID 40486871, 2025). "In metastatic bladder cancer, exemplified by the T24T cell line, miR-145 upregulates FOXO1 expression by inhibiting the phosphorylation of STAT3 at the Tyr705 site, thereby disrupting its repression of FOXO1 transcriptional activity." (PMID 40689207, 2025). "For instance, miR‐204/CD44 axis, miR‐1247‐3p/FOXO1 axis, and miR‐26a‐5p/SLC7A11 axis have been implicated in NSCLC, bladder cancer, and OSCC, respectively." (PMID 39177014, 2024). "In concert with downregulated PI3K/Akt/mTOR signaling, ISO has been previously reported to increase the expression and activity of FOXO1 and FOXO3a in bladder cancer cells." (PMID 38339062, 2024). "The results indicated that SMAD4 and FOXO1 were down-regulated in bladder cancer tissues compared to normal tissues (p < 0.05)." (PMID 36856518, 2023). "In NSCLC and bladder cancers, lower FOXO1 expression was observed in tumor tissues compared to normal tissues." (PMID 37174744, 2023). "We recently reported that ERβ (via binding to its promoter) inactivated FOXO1, a transcription factor shown to function as a suppressor for urothelial tumor, in bladder cancer cells." (PMID 33796076, 2021). "Mechanistically, we found an upregulation of the transcription factor FoxO1 in all three examined bladder cancer cell lines upon epigenetic treatment with DAC, ENT, or the combination of DAC plus ENT." (PMID 32028599, 2020). "We further validated in bladder cancer Umuc-3 and 5637 cells that phosphorylation of Bcl2, Bad, and FoxO1 was consistently repressed by PPARγ agonist rosiglitazone, but enhanced by the inverse agonist T0070907." (PMID 30845932, 2019). "STAT1 has been reported to exhibit a negative regulatory effect on FOXO1 transcription in pancreatic β cells and bladder cancer." (PMID 29796115, 2018). "The expression of FOXO1 was enhanced in superficial bladder cancer when compared with invasive cancer, and compared with the high-grade group (grade 3), expression of FOXO1 was higher in low-grade bladder cancer (grade 1-2)." (PMID 29221208, 2017). "When used for diagnosing bladder cancer, the mRNA expression of FOXO1/3/4 produced cut off values of 1.475, 1.305, and 1.295, respectively, exhibiting relatively high specificity and sensitivity." (PMID 29221208, 2017).